CHD8 (chromodomain helicase DNA binding protein 8)
Description:
ATP-dependent chromatin-remodeling factor, it slides nucleosomes along DNA; nucleosome sliding requires ATP. Acts as a transcription repressor by remodeling chromatin structure and recruiting histone H1 to target genes. Acts as a negative regulator of Wnt signaling pathway by regulating beta-catenin (CTNNB1) activity. Negatively regulates CTNNB1-targeted gene expression by being recruited specifically to the promoter regions of several CTNNB1 responsive genes. Involved in both enhancer blocking and epigenetic remodeling at chromatin boundary via its interaction with CTCF. Acts as a suppressor of STAT3 activity by suppressing the LIF-induced STAT3 transcriptional activity. Also acts as a transcription activator via its interaction with ZNF143 by participating in efficient U6 RNA polymerase III transcription. Regulates alternative splicing of a core group of genes involved in neuronal differentiation, cell cycle and DNA repair. Enables H3K36me3-coupled transcription elongation and co-transcriptional RNA processing likely via interaction with HNRNPL.
Synonyms: HELSNF1; KIAA1564; DUPLIN; AUTS18; IDDAM
Tractability: PROTAC: UniProt records ubiquitination sites on it; ubiquitination databases record sites on it; its protein half-life has been measured.
Target class: Enzyme; Hydrolase
Gene: Protein-coding gene on chromosome 14 (21,385,194 to 21,456,126, reverse strand). Ensembl gene ENSG00000100888.
Subcellular location: Nucleus
Subcellular location (Human Protein Atlas): Nucleoplasm; Plasma membrane; Primary cilium; Primary cilium tip
Pathways (Reactome):
Chromatin organization: CHD6, CHD7, CHD8, CHD9 subfamily
Signal Transduction: Deactivation of the beta-catenin transactivating complex
Gene Ontology:
Molecular function: ATP binding; ATP hydrolysis activity; ATP-dependent chromatin remodeler activity; beta-catenin binding; chromatin binding; DNA binding; histone H3K4me3 reader activity; protein binding; histone binding; ATP-dependent activity, acting on DNA; DNA helicase activity
Biological process: brain development; chromatin remodeling; digestive tract development; mRNA processing; negative regulation of canonical Wnt signaling pathway; negative regulation of DNA-templated transcription; negative regulation of transcription by RNA polymerase II; positive regulation of DNA-templated transcription; positive regulation of transcription by RNA polymerase II; positive regulation of transcription by RNA polymerase III; negative regulation of apoptotic process; negative regulation of Wnt signaling pathway
Cellular component: MLL1 complex; nucleoplasm; nucleus; protein-containing complex; chromatin
Genetic constraint (gnomAD): Loss-of-function variants: 26 observed, 234.81 expected, observed/expected ratio (o/e) 0.11, 90% interval 0.08 to 0.15. The upper end of that interval is the gene's LOEUF score, 0.15, which puts it in group 1 of 6, group 1 being the genes least tolerant of losing a copy. Missense variants: 1,988 observed, 3,052.9 expected, observed/expected ratio (o/e) 0.65, 90% interval 0.63 to 0.68. Synonymous variants: 1,012 observed, 1,104 expected, observed/expected ratio (o/e) 0.92, 90% interval 0.87 to 0.97.
Gene-disease validity (ClinGen):
ClinGen rates the evidence that CHD8 causes each of these diseases.
complex neurodevelopmental disorder (autosomal dominant): Definitive. A disorder that involves more than one phenotype associated with the central nervous system, including but not limited to intellectual disability, autism, and seizures (epilepsy).
Homologues: Orthologues: chimpanzee CHD8 (99% identical), macaque CHD8 (99% identical), pig CHD8 (99% identical), guinea pig CHD8 (97% identical), rat Chd8 (96% identical), mouse Chd8 (96% identical), dog CHD8 (96% identical), rabbit CHD8 (93% identical), tropical clawed frog chd8 (62% identical), zebrafish chd8 (57% identical). Paralogues in human: CHD7 (50% identical), CHD9 (50% identical), CHD6 (42% identical), CHD5 (17% identical), CHD4 (16% identical), CHD3 (16% identical), CHD2 (15% identical), CHD1 (14% identical), SMARCA4 (13% identical), SMARCA2 (12% identical), SRCAP (12% identical), EP400 (12% identical), and 18 more.
Diseases named in the same sentence as CHD8 in open-access papers:
CHD8 is named in the same sentence as 101 diseases in open-access papers, as found by Europe PMC text mining. Sharing a sentence is not in itself a finding about the gene and the disease. The quoted sentences say what the papers report.
autism (97 papers, 2014 to 2025). Persistent deficits in social interaction and communication and interaction as well as a markedly restricted repertoire of activity and interest as well as repetitive patterns of behavior. "Five impacted genes have previously been associated with both autism and DM, including CHD8 and PTEN." (PMID 39887636, 2025). "Taken together, by characterizing mouse models of Treg-specific deletion of autism-associated CHD8, we demonstrated that CHD8 plays an important role in maintaining Treg fitness, by manipulating genetic and epigenetic programs, to control autoimmunity." (PMID 40155813, 2025). "The CHD8 gene is located on chromosome 14 at the 14q11.2 region and is the most frequently mutated gene in autism and other neurodevelopmental disorders." (PMID 40981259, 2025). "Autism patients with CHD8 mutations have a distinct clinical phenotype, which often includes brain overgrowth." (PMID 40104050, 2025). "Chromodomain helicase DNA-binding protein 8 (CHD8) is one of the first genes where mutations were identified as a monogenic cause of autism and to date CHD8 is in the top 5 of the most frequently mutated genes in autism patients." (PMID 40104050, 2025). "Mutations in CHD8 have been strongly associated with a subset of autism cases, often presenting with macrocephaly, developmental delay, ataxia, and distinct facial features." (PMID 40981259, 2025). "It is also linked to autism and intellectual disability, with research showing that CHD8 mutations in mice lead to anxiety and depression-like symptoms." (PMID 41280439, 2025). "For example, loss of function mutations in the autism-associated CHD8 gene is highly penetrant for trait and behavioral abnormalities in children, but there is substantial clinical heterogeneity in the occurrence and extent of disruptions between individuals." (PMID 40092436, 2025). "Mutations in ATP-dependent chromatin remodeler CHD8 cause one of the most frequent monogenetic forms of autism and are associated with brain overgrowth." (PMID 40104050, 2025). "Given CHD8's strong association with autism and macrocephaly, the presence of microcephaly in our case suggests either a unique consequence of the p.(Gln392Ter) variant or the impact of other contributing factors." (PMID 40019509, 2025). "For example, heterozygous knockout of the autism-associated gene CHD8 has varying effects in 33 sub-strains, mirroring heterogeneity observed in human CHD8 haploinsufficiency." (PMID 41306817, 2025). "Chromatin remodeler chromodomain helicase DNA-binding protein 8 (CHD8) defines a subtype of autism that is associated with immune disorders." (PMID 40155813, 2025). "In this study, we sought to determine the function of CHD8 in spermatogenesis, in part because of the epidemiological association between intellectual disabilities including autism, and low fertility." (PMID 38224953, 2024). "Unsurprisingly, as one of the major autism-causing proteins, CHD8 was highly expressed in the nervous system, in the cerebrum and cerebellum." (PMID 38224953, 2024). "Heterozygous, de novo, loss-of-function variants of the CHD8 gene are associated with a high penetrance of autism and other neurodevelopmental phenotypes." (PMID 38288845, 2024). "In zebrafish embryos, morpholino (MO)-mediated knockdown of CHD8, a chromatin-binding protein that targets many other autism-related genes, results in macrocephaly consistent with human autism cases with CHD8 loss of function." (PMID 38542432, 2024). "The chromatin remodeler chromodomain helicase DNA-binding protein 8 (CHD8) is primarily known as an autism gene because it is frequently found mutated in individuals with autism spectrum disorder (ASD)." (PMID 38224953, 2024). "Here we focus on the function of one of the major autism genes, CHD8, in spermatogenesis, based on the epidemiological association between autism and low fertility rates." (PMID 38224953, 2024).
autism (continued). "Here, to tackle this challenge, we took advantage of the strong association between mutations in the autism-candidate CHD8 (chromodomain helicase DNA-binding protein 8; MIM*610528) and GI complaints." (PMID 36375841, 2023). "Arid1b and Chd8 are two of the most frequently mutated genes in autism patients, encode chromatin remodelers, and are widely expressed in many cell types—including granule cells—of the developing and adult cerebellum." (PMID 36865235, 2023). "Several studies have reported links between various severe CHD8 mutations and the incidence of autism." (PMID 37783686, 2023). "Chromodomain helicase DNA-binding protein (CHD8) is among the genes most strongly associated with autism." (PMID 37783686, 2023). "Here, we investigated the role of autism-associated chd8 during the enteric NCC development and in the maintenance of gut homeostasis." (PMID 36375841, 2023). "Chromodomain helicase DNA-binding protein (CHD8) is one of the genes most strongly associated with autism." (PMID 37783686, 2023). "Mutations in the gene encoding chromodomain helicase DNA-binding protein 8 (CHD8) lead to autism symptoms and macrocephaly by a haploinsufficiency mechanism." (PMID 36878905, 2023). "To generate a Chd8 gene-deficient mouse model of autism, we deleted 13 bp from the first exon of the Chd8 gene, resulting in a frameshift mutation and a premature stop codon in Chd8." (PMID 35241668, 2022). "De novo mutations (DNMs) in chromodomain helicase DNA binding protein 8 (CHD8) are associated with a specific subtype of autism characterized by enlarged heads and distinct cranial features." (PMID 36222238, 2022). "Chd8 is an enzyme involved in chromatin remodeling during cerebral fetal development and its mutations are some of the principal causes of autism." (PMID 36613513, 2022). "In a cohort of ~6000 individuals with autism, 0.2% had de novo mutations specifically in CHD8, further demonstrating that CHD8 dysfunction is an important factor in ASD pathology." (PMID 34440307, 2021). "It has been reported that mice carrying heterozygous mutations or gene knockdown of Chd8 display various autism-like phenotypes, such as macrocephaly, social deficits, repetitive behavior, and cognitive impairments." (PMID 33933000, 2021). "Mutations in CHD8 were most frequently associated with autism, followed by macrocephaly, a phenotype also observed in patients carrying a balanced translocation disrupting CHD8." (PMID 33806835, 2021). "Taken together, these two studies suggest that a shift toward GABAergic neuron fate is common to both individuals with CHD8 mutations and idiopathic autism." (PMID 33806835, 2021). "Our findings identify an important role for the autism-associated factor CHD8 in controlling the proliferation of intermediate progenitors in the mouse neocortex." (PMID 33627187, 2021). "A body of recent studies further supports that disruptive de novo mutations of CHD8 underpin a neurodevelopmental syndrome with the leading symptoms of autism and macrocephaly." (PMID 33806835, 2021). "Chromodomain-helicase-DNA-binding protein 8 (CHD8) has been identified as one of the genes with the strongest association with autism." (PMID 34440307, 2021). "In summary, compelling genetic and clinical evidence supports a role of de novo mutations in CHD8 as genetic cause of a distinct subtype in ASD that includes the core symptoms of autism, macrocephaly, and facial dysmorphism." (PMID 33477995, 2021).
autism (continued). "CHD8 haploinsufficiency causes autism and macrocephaly with high penetrance in the human population." (PMID 33627187, 2021). "Initially, we will recapitulate key findings of CHD8 in terms of its gene-regulatory role and as a genetic cause of a distinct neurodevelopmental syndrome with the leading symptoms of autism, macrocephaly, and facial dysmorphisms." (PMID 33806835, 2021). "Individuals with CHD8 mutations show leading symptoms of autism, macrocephaly, and facial dysmorphisms." (PMID 33806835, 2021). "Mutations in the chromodomain helicase DNA-binding protein 8 (CHD8) gene are associated with the classic form of autism, together with macrocephaly, distinct dysmorphic facial features, and gastrointestinal disturbance." (PMID 32309624, 2020). "For other well-described high impact ASD risk genes, such as CHD8, inherited disrupting mutations have been described in families where carrier parents presented with mild NDDs, such as borderline IQ and broader autism phenotypes." (PMID 33391157, 2020). "CHD8 appeared to inhibit the target genes of Wnt/β-catenin, with many other CHD8 targets involving autism risk genes." (PMID 32244359, 2020). "The first report using CRISPR/Cas9 to study the ENS came when the autism-associated gene Chromodomain Helicase DNA Binding Protein 8 (chd8), was knocked out in zebrafish, leading to a reduction in the number of enteric neurons." (PMID 33553169, 2020). "As the child nodes of hub genes, these genes are directly regulated, including known AD-related genes (GABRA1, SYN1, SORSC3, STXBP) and autism risk gene (CHD8)." (PMID 33298176, 2020). "Mutations in CHD8 cause an early-onset form of autism, presenting with a facial phenotype, macrocephaly, and gastrointestinal problems." (PMID 33553169, 2020). "Another example is a recent study that analyzed the co-expression pattern of chromodomain helicase DNA-binding protein 8 (CHD8), a key autism-associated gene." (PMID 31655213, 2019). "Patients with CHD8 mutations are characterized by a high incidence of autism, macrocephaly, facial dysmorphisms, motor delay and hypotonia, intellectual disability, and gastrointestinal problems." (PMID 29668850, 2018). "Structural alterations of these brain areas have been implicated in autism providing potential neural substrates for the autism phenotype associated with CHD8 haploinsufficiency in humans." (PMID 29668850, 2018). "Those with autism and extreme macrocephaly are at a greater risk to have PTEN tumor suppressor gene mutations, while another autism-related gene (CHD8) can also lead to macrocephaly and autism." (PMID 25803107, 2015). "Autism genes converge in midfetal cortical co-expression networks, and chromatin regulators such as CHD8 are increasingly associated with autism spectrum disorder (ASD)." (PMID 25752243, 2015). "Depletion of CHD8 in both mouse and human NSCs causes dysregulation of other autism genes." (PMID 40104050, 2025). "Our findings suggest that the neuroinflammatory processes in patients with autism may be attributed to CHD8 deficiency in Tregs." (PMID 40155813, 2025). "Indeed, the role of one of the first identified large-effect autism genes, CHD8, has been elaborated in zebrafish, where disruption of chd8 caused reduced colonization of enteric neurons into the gut as well as gut dysmotility." (PMID 40050271, 2025). "Patients with CHD8 mutations often present with a distinctive phenotype, which includes not only the typical features of autism, such as social communication deficits and repetitive behaviors, but also macrocephaly, craniofacial abnormalities, intellectual disability, and overgrowth." (PMID 40155813, 2025). "Some CHD8 gene mutations lead to neurodevelopmental syndromes with core symptoms of autism." (PMID 39685474, 2024). "Identifying the neurodevelopmental functions of high-confidence autism risk genes like CHD8 may improve our understanding of the neurodevelopmental mechanisms that underlie autism spectrum disorders." (PMID 38288845, 2024).